IL10 (interleukin 10)
Diseases named in the same sentence as IL10 in open-access papers (continued):
Sharing a sentence is not in itself a finding about the gene and the disease.
bacterial infection (continued). "Hence, the IL-15R/STAT3/IL-10R pathway described here appears to be a unique driver of NK cell IL-10 production during bacterial infection." (PMID 31552035, 2019). "In particular, a shift to glycolysis, which is shown to be altered in cord blood-derived MΦ(IL-10) and in MΦ(IFN-γ) macrophages, is associated with acute bacterial infections and attenuation of glycolysis reduces inflammatory cytokine production and bacterial killing." (PMID 30976008, 2019). "Given that IL-10 has been recognized as an effective anti-inflammatory reagent for bacterial infection, we determined whether IL-10 was present in the peritoneal fluid and serum collected from NV-treated mice at 6 h post-OMV administration." (PMID 31370884, 2019). "To further evaluate whether CB is capable of regulating the expression of IL-8 and IL-10 in bacterial infection, we investigated the effect of feed supplementation of CB in yellow catfish challenged by AP." (PMID 31317044, 2019). "In addition, we thought it unlikely that IL-10 levels would increase, which typically occurs in the presence of a bacterial infection." (PMID 31689293, 2019). "However, pDCs induced a prominent Th2-like profile compared with CD11c+ DCs (higher secretion of IL-4, IL-5, and IL-10), suggesting different contributions to immune regulation in the context of bacterial infection." (PMID 31017904, 2019). "In a previous report we described opposing roles of IL-10 production during bacterial infection." (PMID 30279680, 2018). "In summary, our findings reveal previously unknown roles of c-Fos in the regulation of TLR-4 and IL-10 signaling, which are crucial for B. abortus internalization and growth in macrophages, suggesting a similar role for c-Fos in other bacterial infections." (PMID 30186773, 2018). "On the cellular level, reduction of IL-10 demonstrated that B-2Ta could relieve inflammation by targeting the bacterial infection." (PMID 29340060, 2017). "Low concentrations of IL-10 in plasma may diminish suppressive activity of immune responses, resulting in augmentation of pro-inflammatory activity, and control of bacterial infection." (PMID 28475641, 2017). "IL-10 is also thought to play an important regulatory role in many bacterial infections." (PMID 28951522, 2017). "On the other hand, IL-10 showed greater sensitivity among culture-confirmed bacterial infections." (PMID 28148470, 2017). "Mechanistically, PKCtheta exerts a host-protective role against S. typhimurium infection, and acts as an essential link between TLR4/IFNgammaR signaling and selective suppression of the anti-inflammatory cytokine IL-10 at the onset of CAM differentiation in the course of a bacterial infection." (PMID 27465248, 2016). "IL-10-production by NK cells has been shown to occur in other systems, but our studies are first to show how this “regulatory” response impacts the course of a bacterial infection." (PMID 27295349, 2016). "Blockade of IL-10 signalling clears chronic viral and bacterial infections." (PMID 27100390, 2016). "How does NK cell-derived IL-10 suppress resistance to bacterial infection?" (PMID 27295349, 2016). "An increase in IL-10 might be a disadvantage for the host in terms of bacterial clearance during acute bacterial infections." (PMID 25893429, 2015). "Ly6C- monocytes secrete anti-inflammatory cytokine, IL-10 upon in vivo bacterial infection." (PMID 24398220, 2014). "Collectively, this supports the use of IL-10 as a useful biomarker of bacterial infection." (PMID 24454904, 2014). "The effects of IL-10 during bacterial infections are complex." (PMID 22347396, 2012). "We have previously shown that in adult mice GBS glycolytic enzyme glyceraldehyde-3-phosphate dehydrogenase (GAPDH) is an extracellular virulence factor that induces production of the immunosuppressive cytokine interleukin-10 (IL-10) by the host early upon bacterial infection." (PMID 22114550, 2011).
bacterial infection (continued). "Interleukin-10 has emerged as an essential immunoregulatory cytokine during bacterial infections." (PMID 20398313, 2010). "This signaling loop ultimately enhances IL-10 expression,establishing a positive feedback mechanism critical for dampening inflammation.However, prolonged and excessive activation of this circuit significantlyincreased bacterial load in a model of bacterial infection." (PMID 40026520, 2025). "As IL-10 is a cytokine that inhibits inflammation and promotes the production of anti-inflammatory cytokines such as IL-2 and TNF-α, these results suggest that B102 and B116 may help reduce inflammation caused by bacterial infections in the gut." (PMID 41114506, 2025). "In addition, no significant changes were observed in the anti-inflammatory cytokine IL-10, indicating that N. cochenillifera intake may shift the innate immune function to a higher innate immune response, at least with respect to bacterial infection." (PMID 39770998, 2024). "Therefore, the increased mortality rate could be due to delayed or inadequate treatment of bacterial infections, so that the bacterial load in the blood, and consequently IL-10, remained significantly elevated." (PMID 36275812, 2022). "The balance between pro- and anti-inflammatory signals, such as IL-10, TGFβ and factors released from regulatory T cells, decides about the outcome between immunity and immunopathology to viruses, and generation of regulatory macrophages restricts immunity to bacterial infection." (PMID 22629382, 2012). "Immunosuppressant therapy may downregulate NOD2 expression in CD8+ T lymphocytes, monocytes, and DCs in SLE patients which subsequently IL-10 reduction, contributing towards the regulation of immunopathological mechanisms of SLE, at the expense of increasing risk of bacterial infection." (PMID 21886831, 2011). "The data presented in this study suggests intricate immune modulation of macrophage responses to bacterial infections, particularly in relation to TNF-α, IL-6, IL-10, and IL-12A cytokine profiles." (PMID 40873569, 2025). "Collectively, IL-10 and TNF-α form a critical immune regulatory pathway against bacterial infections." (PMID 41463795, 2025). "In our study, compared with healthy pregnant women, we observed a significant increase in IL‐2, IL‐6, IL‐10 and IFN‐γ in pregnant women with both influenza A and bacterial infection but lower levels of TNF‐α in both groups." (PMID 37638092, 2023). "In addition, IL-10 mediate the immune responses of bacterial infections, as demonstrated in fish and exemplified in sea bass (Dicentrarchus labrax L.) and Indian major carp (Catla catla), in which bacteria successfully induced IL-10 expression in the kidney (an immune organ)." (PMID 37513733, 2023). "In this study, we show that GBS HylB mediates immune suppression and promotes bacterial infection during pregnancy that requires TLR2, TLR4, and IL-10." (PMID 37747229, 2023). "The IL-6, IL-10 and TNF cytokines are produced by activated macrophage cells as a positive response of inflammatory reactions in the process of bacterial infection." (PMID 35369436, 2022). "It performed much better to help to diagnose bacterial infection than other inflammatory biomarkers such as CRP, PCT, and IL-10." (PMID 35391735, 2022). "Increased IL-6, IL-8, IL-10 and TNF-α concentrations have been reported following surgical procedures and in the early stages of bacterial infections both in adults and children." (PMID 36154663, 2022). "For patients with EBV infection, besides IL-6 and IL-10, IFN-γ usually elevated, which is different from bacterial infection." (PMID 35391735, 2022). "Following bacterial infection, BDNF pretreatment reduces the expression of TNF-α, IL-16, IL-1β, and the NFκB pathways, and increases IL-10 and Trk expression." (PMID 34831151, 2021). "Bacterial infection first activates the host’s innate immune response, producing a series of inflammatory cytokines, such as TNF-α, IL-6, and IL-10." (PMID 32913259, 2020).
bacterial infection (continued). "Since A54970 strain failed to trigger IL-1β production, induced high levels of IL-10 and seems to be more susceptible than A28006 strain to microbicidal activity, we investigated the polarization of macrophages into M1 and M2 phenotype post bacterial infection." (PMID 30518854, 2018). "Therefore, we investigated using human B cells whether T‐cell‐independent factors ‐promoting cell survival, class switching and immunoglobulin secretion‐ BAFF, APRIL, IL‐10 and retinoic acid can boost IgA production in the context of viral or bacterial infection." (PMID 28921509, 2018). "Apart from IFN-γ, IL-4 and IL-10, there are several cytokines, such as IL-12, IL-2, IL-1, IL-18 and TNF-α that are involved in the regulation of immune responses to bacterial infections." (PMID 26619346, 2015). "By our study, we also demonstrated that EPs 7630 preincubation of immune cells influenced their subsequent, by viral or bacterial infection-mimicking agents induced cytokine production towards an IL-6-dominated milieu, with lower TNF-α and IL-10 content." (PMID 26406906, 2015). "Bacterial infection led to a significant increase in the levels of pro-inflammatory factors, such as TNF-α, Il-1ꞵ, and IL-6, while the level of the anti-inflammatory factor IL-10 decreased." (PMID 40713896, 2025). "The observed upregulation of il-10 further indicated that NPY could facilitate the resolution phase of inflammation, contributing to immune homeostasis during bacterial infection." (PMID 41007974, 2025). "However, IL-10 can also act as a pro-inflammatory cytokine, particularly with respect to CD8+ T cell function in certain bacterial infections." (PMID 38846955, 2024). "Accumulating evidence has shown that levels of inflammatory biomarkers, including WBC, CRP, NE%, ESR, PCT, IL-6, and IL-10, were significantly higher in patients with bacterial infection than those with non-bacterial infection." (PMID 37986183, 2023). "Microbial products and bacterial infections may stimulate disease progression in CTCL because both, strong activation of STAT-3 and high expression of IL-10, were identified as markers of poor response to treatment in CTCL." (PMID 35267632, 2022). "In this study, we found that IL-10 had some predictive effect on bacterial infection and respiratory bacterial infections, but its AUC did not have a strong advantage over body temperature, CRP, and PCT." (PMID 35463642, 2022). "For non-NPMODS patients, “IL-6 IL-10 ratio” after G- bacterial infection was statistically higher (p < 0.05) with a non-overlapping confidence interval (4.295, 95% CI 3.16–8.27) compared to G+ bacterial infection (2.470, 95% CI 1.37–3.18)." (PMID 36544765, 2022). "We also observed induced protein and mRNA production such as NOD1, IL-10, MCP-1, NOD2, and RIP2 in RAW 264.7 cells under MOMP stimulation compared to normal cells, which are thought to be involved in various immune responses against bacterial infection." (PMID 34812410, 2021). "In this context, it is noted that the absence of IL-10 results in severe pathological changes in different bacterial infections." (PMID 34992597, 2021). "Relative gene expression and protein level of pro-inflammatory cytokines (TNF-α, IL-6, IL-8), IL-10, TLR-2 and SERT were measured in fully differentiated Caco-2 monolayers following 24 h of bacterial infection in the presence of different levels of 5-HT (0, 100, 250, 500 ng/mL)." (PMID 34799637, 2021). "At that time, the differences in PCT and IL-10 were substantial within the two groups, suggesting that patients in the CVD group had a higher risk of bacterial infection than those in the non-CVD group." (PMID 33040051, 2020). "Even though the A54970 strain induces high expression of IL-10, we were not able to distinct M1 and M2 phenotypes under this bacterial infection." (PMID 30518854, 2018).
bacterial infection (continued). "Compared with patients with other bacterial infections, those with β-haemolytic streptococcal infection had higher levels of IL-6, IL-10 and TNF-α but not a higher IL-1β level." (PMID 28176831, 2017). "We found significant differences in IL-6, IL-10 and LBP concentrations between patients with unknown pathogens and those with typical bacterial infections." (PMID 22348735, 2012). "Indeed, knockout SPP1-/- mice have shown significantly impaired Th1 immunity to viral and bacterial infections with diminished production of interleukin-12 (IL-12) and interferon-gamma (IFN-γ) and elevated production of interleukin-10 (IL-10)." (PMID 19765294, 2009). "Moreover, viral and bacterial infections play a crucial role in exacerbating CRS, where IL-10 demonstrates potential therapeutic value in regulating inflammation and ADs by modulating M2 macrophages and mitigating bacterial inflammatory responses triggered by Toll-like receptor signaling." (PMID 39104791, 2024). "We then tested the performance of CRP, IL-6, and IL-10 to predict bacterial infection; the AUCs of CRP, IL-6, and IL-10 were 0.614 (95% CI, 0.531–0.697), 0.703 (95% CI, 0.626–0.780), and 0.657 (95% CI, 0.577–0.737), indicating IL-6 was the most powerful biomarker to predict bacterial infection." (PMID 35391735, 2022). "Looking specifically at the clinical variables shown to predict bacterial infection in the larger Australian PICNICC study cohort (platelets, elevated temperature and clinically unwell) we observed no additional benefit to the high sensitivity and specificity PCT and IL-10 combination." (PMID 34093531, 2021). "In contrast, IL-10 does not have a similar effect in MDR bacterial infections." (PMID 32974363, 2020). "The effects of IL-10 overexpressing MSCs in the setting of live bacterial infection are not known." (PMID 31200579, 2019). "The reduced levels of IL-10 in aged mice may therefore suggest a lack of immunoregulation in the lungs following bacterial infection, thereby contributing to enhanced recruitment of neutrophils and inflammatory disease." (PMID 25595646, 2015). "However, although γδ T cells from the liver can produce IL-10 following bacterial infection, we found that γδ T cells do not produce IL-10 themselves, but induce production from other cells, likely skin-resident myeloid cells such as Langerhans cells and dermal DC." (PMID 38543790, 2024). "Thus, the balance between IL-10 and TNF-α seems to be important for immune homeostasis maintenance, as demonstrated by a curative effect of blocking of the IL-10 pathway in several models of bacterial infections such as from Listeria, Klebsiella, Pseudomonas, Streptococcus, or Mycobacterium." (PMID 31075981, 2019). "Importantly, during MDR-bacterial infections a differential IL-10 production has been described, compared to non-MDR bacteria, which might be due to virulence factors specific of MDR bacteria that modulate production of IL-10." (PMID 30279680, 2018). "RT-qPCR was performed to explore the expression levels of TLR9, the three components of C1q, arginase, iNOS and IL10 in the WT and NOD mice with or without CpG ODN-simulated bacterial infection." (PMID 27527166, 2016). "This suggests that, under conditions of bacterial infection, where LPS is present, activated Vγ9Vδ2 T cells induce full maturation of DCs into APC that release large amounts of IL-12, no or low amount of IL-10 and promote Th1 response." (PMID 22928003, 2012). "Given evidence that IL-10, a well-described anti-inflammatory cytokine, can be induced downstream of IFN signaling, our findings suggest that IL-10-dependent and independent IFN-mediated mechanisms may play non-redundant anti-inflammatory roles in bacterial infection." (PMID 31385572, 2019).
immune dysfunction (111 papers, 2006 to 2026). "Our findings further reveal that age synergizes with immune dysfunction (e.g., Treg/IL-10 imbalance) to amplify PHN risk, providing a mechanistic basis for targeted interventions." (PMID 40606470, 2025). "Defects in IL-10 signaling are associated with extra-intestinal inflammation, severe infections, and the development of immune diseases." (PMID 40376626, 2025). "As IL-6 is a pro-inflammatory cytokine and IL-10 a globally anti-inflammatory cytokine, it was somewhat expected that elevated IL-10 levels would be associated with immune dysfunction, which was confirmed in this study." (PMID 35976460, 2022). "• Augmented PD-1-related molecule expressions after septic shock are associated with immune dysfunctions such as decreased mitogen-induced lymphocyte proliferation and increased circulating interleukin-10 concentration." (PMID 21418617, 2011). "Imbalances in IL-4, IL-10 and IL-13 levels can cause immune dysfunction, causing APOs." (PMID 41394354, 2025). "Mice with IL-10 deficiency can spontaneously suffer from immune disorders." (PMID 38883815, 2024). "Compared to the CTX group, the serum levels of anti-inflammatory cytokines, including IL-4 and IL-10, were significantly increased in the 2FGF-H group (p < 0.05), suggesting that 2FGF may reverse immune disorders caused by CTX." (PMID 39458546, 2024). "Therefore, we screened pro-inflammatory cytokines IL-1β, TNF-α, and IL-6, which cause immune disorders and amplify inflammation, as well as anti-inflammatory cytokine IL-10." (PMID 31500342, 2019). "The IL-10 deficiency has been reported in a number of immune disorders." (PMID 28086216, 2017). "These EDCs disrupt the normal functioning of hormones in males and elevate the levels of pro-inflammatory cytokines such as IL-1b, IL-2, IL-6, IL-10, and IL-17A, leading to immune system disorders." (PMID 39636940, 2024). "Purpurin played an anti-inflammatory role by inhibiting IL-6, TNF-α, and IL-1β and increasing IL-10, and regulated immune disorder by decreasing the CD4+/CD8+ ratio and increasing the FOXP3 level." (PMID 36615560, 2023). "It is considered to be a T cell-dependent immune disease whose pathogenesis is influenced by cytokines, such as IL-10, IL-17A, IL-17RA, IL-23A and IL-23R." (PMID 34945130, 2021). "Such commonalities between these two groups suggest that Il-10-mediated immune dysfunction reinforced the neurodegenerative cascade in the M83+/+ model." (PMID 33741985, 2021). "TNF-α, IL-1, IL-6, IL-8, and IL-10 can be secreted from monocytes/macrophages, whereby inflammatory cascade activation plays a major role in the development of immune dysfunction and multiple organ dysfunction following polytrauma." (PMID 34876907, 2021). "Numerous studies have pointed out that RCC-related immune dysfunction was attributed to anti-inflammatory cytokines, such as IL-10 produced by M2 macrophage." (PMID 34131104, 2021). "Other immune dysfunctions that were observed included alterations in both pro- and anti-inflammatory markers (IL-18, IL-10, and IFN- γ)." (PMID 32691839, 2020). "As one of the three subgroups of the IL-10 family cytokines classified by function, IL-10 is a pleiotropic candidate gene in the pathophysiological mechanism of various immune disorders." (PMID 32974363, 2020). "The imbalance of proinflammatory cytokines, such as IL-6, TNF-α, IL-1β, and IL-10, was demonstrated that contributed to immune dysfunction and also mediated inflammation of the tissues and organ damage in SLE." (PMID 31886314, 2019). "Our data suggest that the accumulation of IL-10+ plasma cells within the bone marrow contributes to the aging of the immune system and the related immune dysfunctions often observed in older individuals." (PMID 31214168, 2019). "Human CD19+CD24hiCD38hi Breg subsets have been shown to maintain tolerance in immune disorders via the release of IL-10." (PMID 30143054, 2018).